SOCS1 (suppressor of cytokine signaling 1)
Diseases named in the same sentence as SOCS1 in open-access papers (continued):
Sharing a sentence is not in itself a finding about the gene and the disease.
cancer (continued). "These regulatory mechanisms will be lost in cancers with SOCS1 gene repression, raising the threshold level of ROS tolerance and thereby diminishing the cytotoxic effects of endogenous and drug-induced ROS." (PMID 38254783, 2024). "In order to inhibit or restore SOCS1 expression in different cancer cell types, several opposite strategies were applied." (PMID 37720228, 2023). "The correlation between miR-155-5p and SOCS1 mRNA was investigated in MDA-MB-231 cancer cells stimulated with IFN-γ." (PMID 37720228, 2023). "Dysregulation of JAK/STAT mediated by SOCS1 has been demonstrated mainly in cytokine signaling, indicating that the cell proliferation control dependent on SOCS1 has a similar mechanism in the suppression of cancer growth." (PMID 36127737, 2023). "Several studies reported abnormal expression of SOCS1 in several cancer cells, whereas studies also reported inhibition of SOCS1 expression at the mRNA level due to hypermethylation in other cancer cell types." (PMID 37720228, 2023). "As expected, treatment of anti-miR155-transfected cancer cells with citrate-AuNPs also inhibited SOCS1 expression at the protein level (p<0.05)." (PMID 37720228, 2023). "In contrast, other studies reveal that the drugs perform demethylation to restore SOCS1 expression of SOCS1 in cancer cells." (PMID 37720228, 2023). "Several observations correlate miR-155 expression with the JAK–STAT signaling pathway through the inhibition of SOCS1 and Ptpn2, suggesting its deep implication in inflammatory signal pathways and cancer." (PMID 38130990, 2023). "Some studies point out that silencing of SOCS1 in cancer cells improves the sensitivity towards IFNs and suppresses cancer cell proliferation." (PMID 37720228, 2023). "Recent studies have shown that SOCS1 can play a role in cancer by regulating oncogenic signal transduction pathways." (PMID 36199788, 2022). "Based on function, the 12 FRGs can be grouped into four classes: Lipid metabolism (GPX4, LPCAT3, ACSL5, and ACSL6), antioxidant metabolism (CD44, SESN2, and AIFM2), iron metabolism (CISD1 and HSPB1), and cancer metabolism (SOCS1, FH, and G3BP1)." (PMID 34784264, 2022). "The 12 FRGs are divided into 4 categories according to their functions: lipid metabolism (GPX4, LPCAT3, ACSL5, ACSL6), antioxidant (CD44, SESN2, AIFM2), iron metabolism (CISD1, HSPB1), and cancer metabolism (SOCS1, FH, G3BP1)." (PMID 35559049, 2022). "miR-155 overexpression in cancer cells enhances immune cell influx by increasing the production of chemoattractants via suppressing SOCS1 and tilting the p-STAT1/p-STAT3 balance." (PMID 35925680, 2022). "It has been reported that SOCS1 acts as an oncogene in various cancers, but its role in OS is unclear." (PMID 36199788, 2022). "SOCS-1 was downregulated in the multiple types of cancers due to hypermethylation of the CpG island in its gene promoter." (PMID 35733955, 2022). "The identification of a regulatory pathway from RNF7 to SOCS1/JAK/STAT3 is particularly exciting because STAT3 activation is widely observed in several human cancers." (PMID 35562668, 2022). "Because SOCS1 is a regulator of interferon signaling, further studies are required to elucidate its role in cancer immunotherapy." (PMID 35626153, 2022). "Taken together, these results indicate that ANKRD52 regulates cancer immunity mainly through miR-155-mediated silencing of SOCS1." (PMID 34853298, 2021). "Suppressor of cytokine signaling (SOCS) protein family, such as SOCS1 and SOCS3, is reported to be closely correlated with cancer cell proliferation and cancer-associated inflammation." (PMID 33397365, 2021). "Nevertheless, non-coding RNA (ncRNA) regulating SOCS1 promotes the occurrence and development of cancers." (PMID 34398824, 2021). "We demonstrate that disruption of the machinery mitigates miR-155-targeted silencing of SOCS1 in cancer cells, and consequently suppresses essential signaling for T cell-mediated anti-tumor immunity." (PMID 34853298, 2021).
cancer (continued). "We demonstrate that the core miRNA biogenesis and targeting machinery are essential for the IFNγ-activated JAK-STAT signaling and antigen presentation in cancer cells, largely by controlling miR-155-targeted silencing of SOCS1." (PMID 34853298, 2021). "Like ANKRD52, transcript levels of these core miRNA processors negatively correlate with the SOCS1 level in a large number of human cancer types." (PMID 34853298, 2021). "Among LS samples, NTSR1, SOCS2, and SOCS1 showed tentatively increased methylation frequencies in carcinomas compared to normal mucosae, but only NTSR1 remained significant after adjustment for multiple testing (p = 0.037)." (PMID 34680073, 2021). "In NSCLC, miR-21 is a serum biomarker for detection of early-stage NSCLC, and has been found to enhance cancer progression by targeting its targets genes, like SOCS1, PTEN, SOX7." (PMID 33081752, 2020). "Pathway enrichment analysis not only suggested that SOCS1 was closely related to cancer but also showed that SOCS1 had a regulatory effect on the cell cycle." (PMID 32096766, 2020). "SOCS1 can bind to FcεRI and is necessary for tumorigenic and metastatic potential of cancer cells enhanced by PSA." (PMID 31597362, 2019). "Several studies found that the promoters of SOCS1 gene were often hypermethylation in some human cancers." (PMID 31728180, 2019). "Because we observed low levels of PD-L1 on both LLC-NT and LLC-sh21 cancer cells in vivo, we wanted to determine if expression of PD-L1 on non-cancer cells was altered in mice implanted with LLC-sh21 Socs1-KD cancer cells." (PMID 31133614, 2019). "This is not observed if LLC-sh21 cells are implanted subcutaneously, suggesting that silencing Socs1 alters communication between cancer cells and specific components of the lung microenvironment that are not present in subcutaneous tumors." (PMID 31133614, 2019). "Cancer tissues exhibited a lower level mRNA expression of SOCS-1 and SOCS-3 than percarcinoma tissues, however this difference was not statistically significant." (PMID 30788302, 2018). "Consistently, these findings consider miRNA-155 and its target SOCS1 as key regulators of effector CD8+ T cells that can be modulated to potentiate immunotherapies for cancers." (PMID 30619765, 2018). "Of the 72 patients, 63 cancer tissues (87.5%) and 54 pericarcinoma tissues (75.0%) expressed SOCS-1 mRNA (RI, 0.459±0.284 and 0.548±0.312, respectively; t=1.957, P=0.054)." (PMID 30788302, 2018). "It would be necessary to identify cytokines that are regulated by SOCS1 for better understanding of interaction between cancer cells and mast cells." (PMID 28968979, 2017). "SOCS1 is necessary for cellular interaction involving cancer cells and mast cells and for cellular interaction involving macrophages and mast cells." (PMID 28968979, 2017). "The abnormal expression of SOCS1 and SOCS3 in cancer cells is associated with the dysregulation of cell growth, migration, and death induced by multiple cytokines and hormones in human carcinomas." (PMID 28228755, 2017). "Given that the expression of SOCS1 is regulated at post-transcriptional level by microRNAs, detection of SOCS1 protein in cancer tissues would represent a direct approach to evaluate SOCS1 as a potential cancer biomarker." (PMID 28235401, 2017). "SOCS1 and SOCS3 are tightly linked to cancer cell proliferation, as well as cancer-associated inflammation." (PMID 29312162, 2017). "SOCS1 and miR-122 regulated cellular interactions involving cancer cells, mast cells and macrophages during allergic inflammation." (PMID 28968979, 2017). "SOCS1 was necessary for allergic inflammation-promoted enhanced tumorigenic and metastatic potential of cancer cells." (PMID 28968979, 2017). "Histone acetylation, deacetylation, and hypermethylation have been previously reported to regulate SOCS1 expression in cancer cells." (PMID 29235573, 2017).
cancer (continued). "While the prostein staining is highly specific to the prostatic epithelium and carcinoma as expected, the SOCS1 Ab also stained immune and stromal cells surrounding the gland and around the prostatic ducts." (PMID 28235401, 2017). "Nonetheless, low SOCS1 expression in cancer specimens showed a weak but significant correlation with lymph node and distant metastasis, and tumour stages of the disease." (PMID 26391193, 2015). "Furthermore, SOCS1 overexpression in a rat model of intestinal epithelial cells (IEC-6) transformed by an oncogenic form of the Met receptor (Tpr-Met-IEC631) promoted these same cancer features, in addition to enhance loss of contact inhibition, as determined in focus assays, and migration." (PMID 26391193, 2015). "We next investigated if the modulation of SOCS1 expression had any impact on the cancer features of the CT26 and CT36 cells." (PMID 26391193, 2015). "Despite previous observations of SOCS1 pro-oncogenic functions in various cancer cell types, the molecular mechanisms remained undefined." (PMID 26391193, 2015). "In sharp contrast, the role of SOCS1 in other types of cancer, including CRC, is understudied and conflicting." (PMID 26391193, 2015). "Similar to the regulation of SOCS in other types of cancer, DNA methylation contributed to SOCS1 downregulation in CaSki, ME-180, and HeLa cells." (PMID 25849377, 2015). "Both SOCS1 and p16 are commonly silenced in malignant tumors, and are also silenced by methylation in familial MM." (PMID 25289094, 2014). "Suppressors of cytokine signaling (SOCS) are transcriptionaltargets of activated STAT proteins that negatively control STAT signaling.SOCS1 expression is silenced in multiple human cancers suggesting a tumorsuppressor role for this protein." (PMID 20622265, 2010). "Our data also support the observations that cancer cells vary in the steady-state level of SOCS1." (PMID 40512405, 2025). "Since miR-146 can suppress SOCS1, miR-146 can potentially promote cancer cell growth." (PMID 40940831, 2025). "The regulation of mitochondrial ROS generation could be one of the reasons why SOCS1 expression is widely repressed in diverse cancers; however, further studies employing diverse growth stimuli are needed to test this hypothesis." (PMID 38254783, 2024). "Mouse cancer models with Socs1 gene repression remain scanty." (PMID 38415248, 2024). "SOCS1 inhibition by miR155 also occurs commonly in several cancers." (PMID 38415248, 2024). "Even though silencing SOCS1 in dendritic cells has been shown to enhance antigen presentation and antitumor immunity, SOCS1 may play an opposite role in cancer cells." (PMID 38415248, 2024). "Larger cohort studies, i.e. of the presently increasing number of SOCS1-HI patients may shed light on this matter and unveil specific cancer occurrences." (PMID 38711523, 2024). "Moreover, some studies have described the role of SOCS1 in the development and progression of cancer." (PMID 39596207, 2024). "As the SOCS1 gene repression mainly occurs via CpG methylation in diverse cancers, demethylating agents such as 5-azacytidine and decitabine could be potentially useful to restore regulated SOCS1 expression." (PMID 38415248, 2024). "Moreover, SOCS1 plays a pivotal role in controlling inflammation, a critical factor in cancer development." (PMID 38711523, 2024). "Cervical cancer-secreted exosomal miR-1468-5p epigenetically activates the JAK2/STAT3 pathway in lymphatic endothelial cells by directly targeting homeobox containing 1 (HMBOX1) in the SOCS1 promoter, activating an immunosuppressive program that allows cancer cells to escape anti-cancer immunity." (PMID 36358833, 2022). "Abnormal expression of SOCS1 is involved in the occurrence and progression of human cancers." (PMID 35562668, 2022).
cancer (continued). "CRC cell-derived miR-146a-5p and miR-155-5p can be taken up by cancer-associated fibroblasts (CAFs) via sEVs and act through the JAK2-STAT3/NF-KB signaling pathway to suppress suppressor of cytokine signaling 1 (SOCS1) and zinc finger and BTB domain-containing 2 protein (ZBTB2)." (PMID 36552835, 2022). "•Downregulating SOCS1 enhances IFN-induced ISGylation which could have implications in cancer development." (PMID 36439639, 2022). "Given the reported roles of STAT3 in cancers, in which RNF7 overexpression has also been observed, it will be interesting to examine whether the regulation of SOCS1/JAK/STAT3 by RNF7 also operates in other cancer types." (PMID 35562668, 2022). "However, the translational or posttranslational regulation of SOCS-1 in cancers has rarely been reported." (PMID 35733955, 2022). "Genetic inactivation of the machinery or re-introduction of ANKRD52 frequent patient mutations dampens the JAK-STAT-interferon-γ signaling and antigen presentation in cancer cells, largely by abolishing miR-155-targeted silencing of suppressor of cytokine signaling 1 (SOCS1)." (PMID 34853298, 2021). "Meanwhile, lower protein expression of SOCS1 and Foxp3 was only evident in both cachectic cancer groups without any association between TAB2 protein expression and the presence of cachexia." (PMID 34900737, 2021). "Although expression levels of individual miRNA machinery components are inversely correlated with SOCS1 in many human cancer types, inactivation of the core miRNA pathway should block silencing of many more genes in addition to SOCS1 for immune response, which still need to be further elucidated." (PMID 34853298, 2021). "Similarly, dormant cancer cells escape T cell induced apoptosis by deregulating the suppressor of cytokine signaling 1 (SOCS1) cascade and overexpressing the pro-tumorigenic cytokine interleukin (IL)-3." (PMID 34572009, 2021). "SOCS1 acts as a cancer suppressor by promoting apoptosis and suppressing the metastasis of OS." (PMID 32793475, 2020). "miR-155 overexpression promotes cancer progression via SOCS1 deregulation." (PMID 31718618, 2019). "Downregulation of SOCS1 has been confirmed in various cancer types including TNBC." (PMID 32010177, 2019). "Importantly, cancer cells with Socs1 silencing (LLC-sh21 cells) grown as orthotopic tumors are much more responsive to anti–PD-1 therapy than LLC-NT control tumors." (PMID 31133614, 2019). "Ergo, SOCS1 holds great potential in the treatment of FAK-driven cancers." (PMID 31105556, 2019). "Thus, in LLC-sh21 tumors where cancer cells are silenced for Socs1, there is an increased proportion of PD-L1hi macrophages, with the greatest contribution of PD-L1 expression coming from resident alveolar macrophages." (PMID 31133614, 2019). "Therefore, we selected SOCS1 which was involved in cancer cell proliferation, migration, invasion and drug resistance, as a potential CASC2 target." (PMID 31728180, 2019). "Therefore, pharmacological inhibition of SOCS1 should increase the effectiveness of these types of cancer immunotherapies and the structures of SOCS1 presented here will enable structure-guided drug design approaches towards this aim." (PMID 29674694, 2018). "For instance, in primary cancers retaining SOCS1 expression, MET mutations might allow escape from SOCS1-mediated regulation." (PMID 28235401, 2017). "SOCS1 expression is also inhibited by microRNAs such as miR-19 and miR-155 in human cancers." (PMID 28235401, 2017). "Therefore, it is necessary to carry out prospective studies on SOCS1 protein expression in PCa and other cancers with a wider scope, including treatment responsiveness, disease-free survival and overall survival." (PMID 28235401, 2017). "Next, the effect of SOCS1 on the metastatic potential of cancer cells was examined." (PMID 28968979, 2017). "Alternatively, signaling pathways other than MET might contribute to aggressive growth of cancer cells retaining SOCS1 expression." (PMID 28235401, 2017).
cancer (continued). "SOCS1 mimetic peptide, D-T-H-F-R-T-F-R-S-H-S-D-Y-R-R-I, inhibited in vitro and in vivo allergic inflammation, allergic inflammation-promoted enhanced tumorigenic and metastatic potential of cancer cells, and cellular interactions during allergic inflammation." (PMID 28968979, 2017). "In tumors at early stage, elevated SOCS1 is frequently observed compared with those tumors at advanced stage, which could be regarded as a molecular marker of cancer progression." (PMID 28228755, 2017). "Validated miR-155 target genes are present in multiple pathways associated with cancer and cancer progression, including EMT (SMAD5), proliferation (SOCS1, INPP5D, and CSF1R), block of differentiation (SPI1, CEBPB), and apoptosis (CASP3, FADD, APAF1, and FOXO3A)." (PMID 27128908, 2016). "By reducing intracellular ROS found at abnormally high levels in cancer cells, SOCS1 may exert anti-EMT and anti-invasive functions to prevent malignant progression." (PMID 27613835, 2016). "Notably, changes including elevated levels of expression of Kras and mmu-miR-155 and the repression of Socs1 were observed following genotoxic damage, reflecting induction of a cancer-prone phenotype." (PMID 23496831, 2013). "A previous study focusing on DNA methylation profiles in HCC at a few selected loci of tumor suppressor genes and oncogenes found methylation changes in the promoters of 9 cancer-related genes, including SOCS-1, GSTP, APC, E-cadherin, RAR-beta, p14, p15, p16 (CDKN2A), and p73." (PMID 23437062, 2013). "Thus, relieving the blockade on IFNγ signaling that upregulates the checkpoint ligand could be another reason why cancer cells choose to repress SOCS1 expression by diverse mechanisms." (PMID 38415248, 2024). "Our investigations on the role of SOCS1 in regulating NRF2-mediated oxidative stress response revealed that SOCS1 might also modulate ROS generation and other antioxidant response pathways, which can impact cancer progression and the efficacy of cancer therapies." (PMID 38254783, 2024). "However, it will be a challenging task to introduce SOCS1 mimetic peptides into all cancer cells." (PMID 38415248, 2024). "Therefore, high SOCS1 expression in HNSCC may play a significant role in inhibiting cancer development." (PMID 37504269, 2023). "Therefore, evaluating SOCS1 expression and its correlated functions may have prognostic significance in cancers." (PMID 36127737, 2023). "Besides, other molecules/pathways might influence the downstream mediators of SOCS1 to a variable extent in individual cancers." (PMID 28235401, 2017). "Notably, the SOCS1 gene is frequently silenced in cancer by hypermethylation of its promoter." (PMID 26391193, 2015). "The cross talk between miR-155, SOCS1, and STAT3 signaling may provide a new mechanism for inflammation-associated tumorigenesis, which suggests that miR-155 and SOCS1 could potentially be used in cancer therapy." (PMID 26697428, 2015). "In cancer, antitumor immunity might be inhibited by suppressors of cytokine signaling 1 (SOCS1)." (PMID 22028974, 2012). "Several researchers have also discovered that by targeting the cytokine signaling inhibitor the suppressor of Cytokine Signaling 1(SOCS1), they regulate STAT3-related signaling pathways, ultimately leading to the occurrence and development of cancer." (PMID 39963112, 2025). "Aberrant STAT hyperactivation and consequent SOCS1 or SOCS3 intervention is observed in immune-mediated inflammatory diseases and malignancies of the skin." (PMID 38975347, 2024). "However, in cases where miR-122-5p is elevated, SOCS1 suppression may lead to a constant activation of the JAK/STAT pathway, which is implicated in the pathogenesis of various cancers, including cHL, as it promotes cellular survival, proliferation, immune evasion, and inflammation." (PMID 39769007, 2024).